MCM9 (minichromosome maintenance 9 homologous recombination repair factor)
Description:
Component of the MCM8-MCM9 complex, which is involved in the repair of double-stranded DNA breaks (DBSs) and DNA interstrand cross-links (ICLs) by homologous recombination (HR). The MCM8-MCM9 complex is a 3'-5' DNA helicase and single-stranded (ss)DNA-stimulated ATPase which binds ssDNA in the presence of nucleoside triphosphates. Required for DNA resection by the MRE11-RAD50-NBN/NBS1 (MRN) complex by recruiting the MRN complex to the repair site and by promoting the complex nuclease activity. Indirectly regulates the recruitment of downstream effector RAD51 to DNA damage sites including DBSs and ICLs, probably by regulating the localization of the MNR complex. Acts as a helicase in DNA mismatch repair (MMR) following DNA replication errors to unwind the mismatch containing DNA strand. In addition, recruits MLH1, a component of the MMR complex, to chromatin. The MCM8-MCM9 complex is dispensable for DNA replication and S phase progression. Plays a key role during gametogenesis, probably by regulating HR (By similarity).
Synonyms: C6orf61; MCMDC1; MGC35304; dJ329L24.3; FLJ20170; ODG4; dJ329L24.1
Tractability: Small molecule: a structure with a bound ligand is known. PROTAC: ubiquitination databases record sites on it.
Gene: Protein-coding gene on chromosome 6 (118,813,442 to 118,935,162, reverse strand). Ensembl gene ENSG00000111877.
Subcellular location: Nucleus; Chromosome
Subcellular location (Human Protein Atlas): Nucleoplasm
Gene Ontology:
Molecular function: 3'-5' DNA helicase activity; ATP hydrolysis activity; chromatin binding; DNA helicase activity; enzyme binding; MutLbeta complex binding; MutSalpha complex binding; MutSbeta complex binding; protein binding; protein-containing complex binding; single-stranded DNA binding; single-stranded DNA helicase activity; ATP binding; DNA binding
Biological process: DNA damage response; DNA replication; double-strand break repair via homologous recombination; mismatch repair involved in maintenance of fidelity involved in DNA-dependent DNA replication; protein localization to chromatin; recombinational interstrand cross-link repair; female gamete generation; gamete generation
Cellular component: chromosome; MCM8-MCM9 complex; nucleus; MCM complex
Genetic constraint (gnomAD): Loss-of-function variants: 51 observed, 70.27 expected, observed/expected ratio (o/e) 0.73, 90% interval 0.58 to 0.92. The upper end of that interval is the gene's LOEUF score, 0.92, which puts it in group 3 of 6, group 1 being the genes least tolerant of losing a copy. Missense variants: 1,276 observed, 1,428 expected, observed/expected ratio (o/e) 0.89, 90% interval 0.85 to 0.94. Synonymous variants: 480 observed, 528.92 expected, observed/expected ratio (o/e) 0.91, 90% interval 0.84 to 0.98.
Homologues: Orthologues: chimpanzee MCM9 (99% identical), macaque MCM9 (96% identical), dog MCM9 (81% identical), pig MCM9 (80% identical), rabbit MCM9 (79% identical), mouse Mcm9 (74% identical), rat Mcm9 (73% identical), guinea pig MCM9 (70% identical), tropical clawed frog mcm9 (54% identical), zebrafish mcm9 (49% identical). Paralogues in human: MCM2 (20% identical), MCM8 (20% identical), MCM3 (19% identical), MCM6 (18% identical), MCM7 (18% identical), MCM4 (17% identical), MCM5 (16% identical), MCMDC2 (10% identical).
Diseases named in the same sentence as MCM9 in open-access papers:
MCM9 is named in the same sentence as 52 diseases in open-access papers, as found by Europe PMC text mining. Sharing a sentence is not in itself a finding about the gene and the disease. The quoted sentences say what the papers report.
colorectal cancer (5 papers, 2021 to 2025). A primary or metastatic malignant neoplasm that affects the colon or rectum. "Among the 74 biallelic MCM9 variant carriers in the 200000 UK Biobank, 1 individual (1.4%) was registered with colorectal cancer (CRC), 3 (4%) with colonic polyps, 6 (8%) with adenomas, 1 (1.4%) with rectal polyps, and 2 (2.7%) with hypothyroidism." (PMID 40684266, 2025). "Biallelic MCM9 variants are associated with polyposis, gastric cancer, and early-onset colorectal cancer, while both biallelic MCM8 and MCM9 variants are linked to hypogonadism and the early development of germ cell tumors." (PMID 40684266, 2025). "In humans, pathogenic MCM9 variants appear to be associated with hereditary mixed polyposis and early onset colorectal cancer, causing a Lynch-like syndrome." (PMID 36769638, 2023). "Moreover, carriers of homozygous mutations in MCM9 had a high risk of early colorectal carcinoma and premature ovarian insufficiency." (PMID 34490114, 2021). "In particular, MCM9 recessive mutations cause both POI and colorectal cancer." (PMID 38996041, 2025). "Likewise, in our case series, which included 26 MCM8 and 28 MCM9 variant carriers, we documented polyposis, gastric cancer, and early-onset colorectal cancer (CRC) in MCM9 carriers but not in MCM8 carriers." (PMID 40684266, 2025). "Although MCM9 plays a role in genome maintenance and has been reported as a candidate gene in a few patients with inherited colorectal cancer (CRC), it has not been clearly established as a cancer predisposition gene." (PMID 34556653, 2021).
hypogonadism (3 papers, 2023 to 2025). A disorder characterized by decreased function of the gonads. "Variants of MCM9, a gene essential for DNA repair, had already been associated with hypogonadism in men." (PMID 41488147, 2025). "Collectively, our data indicate that biallelic MCM9 variants are associated with polyposis, gastric cancer, and early-onset CRC, while both biallelic MCM8 and MCM9 variants are linked to hypogonadism and the early development of germ cell tumors." (PMID 40684266, 2025). "The majority of individuals with biallelic MCM8 (23 out of 26, 88%) or MCM9 (26 out of 28, 93%) variants from our case series experienced hypogonadism (HP:0000815)." (PMID 40684266, 2025). "Among the 45 monoallelic MCM9 variant carriers from our case series, 10 (22%) were known to have hypogonadism, including 1 individual who was also diagnosed with CRC and polyposis." (PMID 40684266, 2025). "Our data suggest that biallelic MCM9 variants are associated with polyposis, gastric cancer, and early-onset CRC, while both biallelic MCM8 and MCM9 variants are linked to hypogonadism and the early development of germ cell tumors." (PMID 40684266, 2025). "MCM8 and MCM9 are newly proposed cancer predisposition genes, linked to polyposis and early-onset cancer, in addition to their previously established association with hypogonadism." (PMID 40684266, 2025). "Similarly, the pathogenic c.394C>T [p.(Arg132∗)] variant in the MCM9 gene, also associated with hypogonadism, was shared by seven biallelic carriers from four unrelated families." (PMID 40684266, 2025). "Following the initial discovery of biallelic germline MCM8/MCM9 variants in families with CRC, polyposis, and hypogonadism, we present a comprehensive clinical and molecular characterization of biallelic MCM8/MCM9 variant carriers from multiple sources." (PMID 40684266, 2025). "Moreover, our case series indicates that beyond hypogonadism, biallelic MCM8 and MCM9 variants are associated with early-onset germ cell tumors (occurring before age 15)." (PMID 40684266, 2025). "Furthermore, osteoporosis or delayed bone age (HP:0000939) was reported in seven individuals with biallelic MCM9 variants and one individual with biallelic MCM8 variants, all of whom were affected by hypogonadism." (PMID 40684266, 2025). "Osteoporosis in female POI patients is most likely secondary to severe and prolonged hypogonadism, as a direct role for MCM9 pathogenic variants in the bone has not been described." (PMID 36769638, 2023). "We recommend considering biallelic MCM9 variants in individuals and families with unexplained polyposis, gastric cancer, germ cell tumors, or (early-onset) CRC, particularly in cases of recessive inheritance and known hypogonadism, until more data are available." (PMID 40684266, 2025).
Infertility (3 papers, 2021 to 2024). "Mutations in MCM8 and MCM9 have been clearly linked with infertility and primary ovarian insufficiency as well as predispositions to a variety of cancers." (PMID 36042199, 2022). "By contrast, both male and female humans are infertile if the MCM9 gene is disrupted." (PMID 38540391, 2024).
Azoospermia (2 papers, 2023 to 2025). Absence of any measurable level of sperm,whereby spermatozoa cannot be observed even after centrifugation of the semen pellet. "This is—to our knowledge—the first detailed clinical, hormonal, and gonadal description of a male individual with azoospermia due to a pathogenic variant of the MCM9 gene." (PMID 36769638, 2023). "Two whole-exome sequencing studies analysing the genetic causes of azoospermia or severe oligospermia reported homozygous variants of the MCM9 gene." (PMID 36769638, 2023). "Apart from five males (three with biallelic MCM8 variants and two with biallelic MCM9 variants) with azoospermia (no sperm in the semen; HP:0000027), these issues involved women affected by POI." (PMID 40684266, 2025). "Here, we report the characteristics of subjects with POI and non-obstructive azoospermia due to a homozygous pathogenic truncating MCM9 variant." (PMID 36769638, 2023). "In the male patient the homozygous MCM9 variant led to normal pubertal development and hormonal levels but caused a Sertoli-cell-only syndrome with non-obstructive azoospermia." (PMID 36769638, 2023). "However, the histopathological basis of the non-obstructive azoospermia has never been reported previously in MCM9 mutated subjects." (PMID 36769638, 2023). "Homozygous pathogenic MCM9 variant in the human male is associated with normal pubertal development and hormonal levels but leads to a Sertoli cell-only syndrome causing non-obstructive azoospermia." (PMID 36769638, 2023). "We report a family with a homozygous pathogenic MCM9 variant consisting of three sisters with ovarian dysgenesis and their brother, who is the first male patient with this pathogenic variant and non-obstructive azoospermia due to Sertoli cell-only syndrome that was proven on testicular biopsy." (PMID 36769638, 2023). "We identified a homozygous pathogenic MCM9 variant, c.394C>T (p.Arg132*) in three sisters affected by POI due to ovarian dysgenesis and their brother who had normal pubertal development but suffered from non-obstructive azoospermia." (PMID 36769638, 2023).
cervical cancer (2 papers, 2020 to 2025). A primary or metastatic malignant neoplasm involving the cervix. "TP53BP1, MCM9 (at higher than mean levels), POLR2F and SIRT6 (at lower than mean levels), were associated with an increase in patients experiencing cervical cancer recurrence/progression following postoperative radiation therapy when HPV18 positive, but not HPV16 positive." (PMID 32066835, 2020). "Expression levels of MCM9 and TP53BP1, when higher than the mean expression level, were significantly associated with a poorer outcome for cervical cancer patients if they were HPV18+, yet not HPV16+." (PMID 32066835, 2020). "Moreover, increased expression levels of TP53BP1 and MCM9 and decreased expression levels of POLR2F and SIRT6 were found to be specifically associated with a poorer prognosis for HPV18+ (but not HPV16+) cervical cancer patients following PRT." (PMID 32066835, 2020).
Down syndrome (2 papers, 2021 to 2022). "We hypothesize that the polymorphisms in MCM9 predispose women to experience reduced recombination on chromosome 21 in oocytes at meiosis I, which ultimately leads to the birth of a child with Down syndrome." (PMID 33750944, 2021). "Distribution of MCM9 genotypes among the control mothers (N = 730) and mothers ofchildren with Down syndrome (N = 700) who experienced meiosis I errors." (PMID 33750944, 2021). "Distribution of MCM9 genotypes among the control mothers (N = 730) and mothers of children with Down syndrome (N = 125) who experienced meiosis II errors." (PMID 33750944, 2021). "We studied MCM9 variations in the genome of women with a Down syndrome child by stratifying the women based on MCM9 genotypes, meiotic error group, and their age of conception." (PMID 33750944, 2021). "Recent studies have identified some genetic predispositions (just as consanguineous marriage, maternal telomere length, maternal MCM9 polymorphisms, maternal Presenilin-1 and Apolipoprotein E polymorphisms) of women that may cause nondisjunction and Down syndrome birth at younger age." (PMID 36092906, 2022). "We for the first time genotyped the gene MCM9, a candidate gene for recombination regulation and DNA repair in mothers with or without children with Down syndrome." (PMID 33750944, 2021).
Fanconi anemia (2 papers, 2021 to 2024). Fanconi anemia (FA) is a hereditary DNA repair disorder characterized by progressive pancytopenia with bone marrow failure, variable congenital malformations and predisposition to develop hematological or solid tumors. "In LXF-289 cells, the NHEJ and Fanconi anemia pathways were strongly represented among the top hits enriched, as well as MCM8, MCM9, and HROB, genes that have previously been implicated in HR." (PMID 33788831, 2021). "It has been reported that the MCM8/9 complex participates in interstrand crosslink repair by functioning in RAD51-dependent HR repair downstream of the Fanconi anemia (FA) pathway, and Mcm8 and Mcm9 KO mice share the similar phenotype with FA-null mice of massive loss of proliferating PGCs." (PMID 38858601, 2024).
melanoma (2 papers, 2021 to 2025). A malignant, usually aggressive tumor composed of atypical, neoplastic melanocytes. "Single biallelic MCM9 variant carriers were diagnosed with gastric cancer (HP:0012126), a human papillomavirus-unrelated clear cell carcinoma of the cervix (HP:0031522), and melanoma (HP:0012056), whereas a biallelic MCM8 variant carrier was diagnosed with breast cancer (HP:0003002)." (PMID 40684266, 2025). "In our study, MCM9 was correlated with the T and tumor stages in patients with melanoma." (PMID 34490114, 2021). "The results revealed MCM1–7 protein levels were higher in melanoma tissues than in normal skin tissues, consistent with the results of MCM mRNA expression, whereas MCM9 and MCM10 proteins showed no great difference between melanoma and normal skin." (PMID 34490114, 2021).
osteoporosis (2 papers, 2023 to 2025). A condition of reduced bone mass, with decreased cortical thickness and a decrease in the number and size of the trabeculae of cancellous bone (but normal chemical composition), resulting in increased fracture incidence. "However, as osteoporosis was also found in the younger brother and the father, who were heterozygous for the MCM9 pathogenic variant, this argues against a mechanism via homozygous MCM9 pathogenic variants leading to loss of bone mass in the family." (PMID 36769638, 2023).
ovarian failure (2 papers, 2023 to 2025). "MCM9 functional deficiency is related to ovarian failure and chromosomal instability." (PMID 39949729, 2025).
ovarian tumors (2 papers, 2015 to 2023). "Murine MCM9-deficient models exhibit genome instability and are predisposed to the development of different types of cancers [hepatocellular carcinoma, ovarian tumors]." (PMID 36769638, 2023).
polyposis (2 papers, 2021 to 2025). "We provide clinical evidence for MCM9 as a cancer germline predisposition gene associated with early-onset cancer and polyposis, mainly in a recessive inheritance pattern." (PMID 34556653, 2021). "Similar to the NTHL1- and MUTYH-deficiency syndromes, which are associated with CRC and polyposis, the MCM9-deficiency syndrome observed in our population-based analysis and case series may warrant comparable surveillance protocols." (PMID 40684266, 2025). "Our analysis of the 100000 Genomes Project reveals that biallelic MCM9 variant carriers are at increased risk for polyposis and gastric cancer, a pattern not observed in biallelic MCM8 carriers." (PMID 40684266, 2025).
premature ovarian failure (2 papers, 2020 to 2022). "Regarding MCM9, 2 families carried biallelic genetic variants, including a LLS patient with premature ovarian failure (POF) and a familial MMR-proficient CRC patient, and heterozygote variants were found in 12 patients." (PMID 32841224, 2020).
Premature ovarian insufficiency (2 papers, 2021 to 2023). Amenorrhea due to loss of ovarian function before the age of 40. "Minichromosome maintenance complex component 9 (MCM9) is involved in DNA repair and mutations of the MCM9 gene have been previously reported in females with premature ovarian insufficiency (POI)." (PMID 36769638, 2023).
Sertoli Cell-Only Syndrome (2 papers, 2023 to 2025). A type of male infertility in which no germ cells are visible in any of the biopsied SEMINIFEROUS TUBULES (type I) or in which germ cells are present in a minority of tubules (type II). "Our study identified two novel homozygous loss-of-function (LoF) mutations in MCM9 in two unrelated NOA patients presenting with Sertoli cell-only syndrome (SCOS)." (PMID 40593474, 2025).
breast carcinoma (1 paper, 2025). "Among the 64 biallelic MCM9 variant carriers in the 100000 Genomes Project, 3 individuals (4.7%) had CRC, 2 (3.1%) had colonic polyps, 2 (3.1%) had colonic adenomas, 2 (3.1%) had rectal polyps, 3 (4.7%) had hypothyroidism, 5 (7.8%) had breast cancer, and 2 (3.1%) had epilepsy." (PMID 40684266, 2025).
colorectal tumors (1 paper, 2017). "Interestingly, MCM9, which has a role in the S-phase checkpoint pathways and is often suppressed in colorectal tumors, was upregulated by [Ca2+]o treatment." (PMID 28161520, 2017).
endometrial cancer (1 paper, 2025). Primary or metastatic malignant neoplasm involving the endometrium (mucous membrane that lines the endometrial cavity). "No biallelic MCM8/MCM9 variant carriers meeting the pathogenicity-based filtering criteria were identified in the SPS case group, fCRCX, and HMF (metastasized CRC and endometrial cancer case groups) cancer-specific cohorts." (PMID 40684266, 2025).
familial cancer (1 paper, 2020). "Finally, the presence of MCM8/MCM9 genetic variants in the independent analyzed cohort with a putative involvement in familial cancer/CRC predisposition supports, to some extent, our conclusions." (PMID 32841224, 2020).
germ cell tumor (1 paper, 2025). A benign or malignant, gonadal or extragonadal neoplasm that originates from germ cells. "Three female carriers—two with biallelic MCM8 variants and one with a biallelic MCM9 variant—were diagnosed with germ cell tumors (HP:0100728) between the ages of 11 and 15 years." (PMID 40684266, 2025). "Considering the prevalence of germ cell tumors in female biallelic MCM8/MCM9 variant carriers, annual ultrasound screening starting at age 10 could be considered, given the early onset of 11–15 years observed in our case series." (PMID 40684266, 2025).